IGHV4-31 (immunoglobulin heavy variable 4-31)
Description:
V region of the variable domain of immunoglobulin heavy chains that participates in the antigen recognition. Immunoglobulins, also known as antibodies, are membrane-bound or secreted glycoproteins produced by B lymphocytes. In the recognition phase of humoral immunity, the membrane-bound immunoglobulins serve as receptors which, upon binding of a specific antigen, trigger the clonal expansion and differentiation of B lymphocytes into immunoglobulins-secreting plasma cells. Secreted immunoglobulins mediate the effector phase of humoral immunity, which results in the elimination of bound antigens. The antigen binding site is formed by the variable domain of one heavy chain, together with that of its associated light chain. Thus, each immunoglobulin has two antigen binding sites with remarkable affinity for a particular antigen. The variable domains are assembled by a process called V-(D)-J rearrangement and can then be subjected to somatic hypermutations which, after exposure to antigen and selection, allow affinity maturation for a particular antigen.
Synonyms: IGHV4-3; IGHV4302; IGHV4-30-2
Gene: Immunoglobulin variable (V) gene on chromosome 14 (106,349,283 to 106,349,792, reverse strand). Ensembl gene ENSG00000231475.
Subcellular location: Secreted; Cell membrane
Gene Ontology:
Molecular function: antigen binding
Biological process: immunoglobulin mediated immune response
Cellular component: extracellular region; plasma membrane
Genetic constraint (gnomAD): Missense variants: 49 observed, 26.55 expected, observed/expected ratio (o/e) 1.85, 90% interval 1.43 to 1.97. Synonymous variants: 15 observed, 7.77 expected, observed/expected ratio (o/e) 1.93, 90% interval 1.17 to 1.97.
Homologues: Paralogues in human: IGHV4-39 (92% identical), IGHV4-61 (92% identical), IGHV4-4 (91% identical), IGHV4-59 (91% identical), IGHV4-28 (89% identical), IGHV4OR15-8 (88% identical), IGHV4-34 (87% identical), IGHV6-1 (61% identical), IGHV3-11 (55% identical), IGHV2-5 (54% identical), IGHV2-70 (53% identical), IGHV2-26 (53% identical), and 65 more.
Diseases named in the same sentence as IGHV4-31 in open-access papers:
IGHV4-31 is named in the same sentence as 2 diseases in open-access papers, as found by Europe PMC text mining. Sharing a sentence is not in itself a finding about the gene and the disease.
IGHV4-31 shares sentences with these, for which no sentence is quoted: acute leukemia (1 paper); laryngeal carcinoma (1).